MTOR (mechanistic target of rapamycin kinase)
Diseases named in the same sentence as MTOR in open-access papers (continued):
Sharing a sentence is not in itself a finding about the gene and the disease.
cancer (continued). "Based on the ceRNA network and the results of the functional analysis of hub driving genes, the key genes that enriched in the Wnt, mTOR, and MAPK signaling pathways were picked as subgroup analysis because these signaling pathways were more closely related to cancer and more typical." (PMID 32196072, 2020). "Additionally, in cancer cells, activation of the PI3K/Akt/mTOR signaling pathway can result in inhibiting the effects of Akt on apoptosis and mTOR on autophagy, thus improving cell survival capability." (PMID 32878322, 2020). "Under glutamine deprivation or hypoxic condition, mTOR-mediated NAA10 phosphorylation at S228 residue is downregulated, resulting in the activation of an acetyltransferase activity of NAA10 and the promotion of protective autophagy processes in cancer cells." (PMID 33126484, 2020). "Therefore, we assume that the inducible acquisition of CD44 and its consequences account for the mechanism by which cancer cells reduce PI3Kα inhibition and maintain AKT/mTOR activation." (PMID 33024087, 2020). "In our study, we investigated the MEK inhibitor selumetinib and PI3K/mTOR dual inhibitor BEZ235 alone and in combination in BRAF-only mutant and BRAF + PI3K/PTEN double mutant cancer cells using short- and long-term 2D viability assays, spheroid assays, and immunoblots." (PMID 33081092, 2020). "Taken together, these findings indicate that (P) RR may contribute to cancer development through the MAPK/ERK and PI3K/AKT/mTOR pathways." (PMID 32143717, 2020). "Curcumin, a further well-known phytopolyphenolic compound, has been shown to decrease glucose uptake and lactate production in several cancer cells (lung, breast, cervical, prostate and embryonic kidney cancer cell lines) down-regulating PKM2 expression, interfering with the mTOR-HIF-1α axis." (PMID 32013090, 2020). "Herein, based on previous reports regarding PI3K/Akt/mTOR pathway regulating HIF-1α and HIF-1α promoting Zeb1 expression, we investigated the possible role of neddylation between HIF-1α and ZEB1 regarding cancer cell migration." (PMID 33097763, 2020). "It has been shown that ESRP1/2 activation leads to oncogenic activation of several ESRP1/2 target genes such as MAP 3 K7, mTOR, GSK3ß, RB1, CTNND1, E-Cadherin, and CD44, which drive tumor cell proliferation and EMT, key features of advanced and aggressive cancers." (PMID 33339518, 2020). "mTOR, as key protein of the PI3K/AKT pathway, acts both upstream and downstream of AKT, and aberrant mTOR activation of promotes survival and proliferation of tumor cells in several human cancers." (PMID 32850962, 2020). "However, it can reduce the total protein amount of mTOR and NF-κB, resulting in increased apoptosis in LAT1-expressing cancer cells." (PMID 32405891, 2020). "In addition, Isorhamnetin also down-regulated the expression of phosphorylated PI3K (p-P13K), Akt (p-Akt), and mTOR (p-mTOR) proteins in both cancer cells, revealing Isorhamnetin to be a selective PI3K–Akt–mTOR pathway inhibitor." (PMID 32039440, 2020). "The mTOR inhibition can also activate its downstream target AMPK, which is a sensor of the energetic status of cells and is known to control proliferation in some cancers." (PMID 33028364, 2020). "Although the roles of the mTOR pathway in cancer research have been extensively studied, there has been no in-depth study on the role of mTOR signaling in pain research." (PMID 33267907, 2020).
cancer (continued). "Drugs were selected based on approval for clinical use in CRC or other cancer types (5-FU, oxaliplatin, olaparib, palbociclib), and on their ability to target pathways frequently dysregulated in cancer (MAPK/ERK pathway, PI3K/AKT/mTOR pathway and TGF-beta pathway)." (PMID 32665693, 2020). "Functional enrichment analysis indicated that CKI has a therapeutic effect on GC by synergistically regulating some biological pathways, such as the cell cycle, pathways in cancer, the PI3K-AKT signaling pathway, the mTOR signaling pathway, and the FoxO signaling pathway." (PMID 32020871, 2020). "As we said earlier, curcumin inhibits the Akt-mTOR pathway and interferes with PI3K/Akt signaling, leading to the inhibition of the proliferation and reduction of the invasiveness and migration of various cancer cells, including triple-negative cancer cells." (PMID 32765806, 2020). "ATF6 modulates cancer cell dormancy via the activation of Ras homolog enriched in brain (RHEB) and mTOR, in which ATF6 not only plays a role as a key survival factor for quiescent squamous carcinoma cells, but is also pivotal for the adaptation of dormant cells to chemotherapy." (PMID 31739582, 2019). "A few studies have highlighted the phosphoinositide 3 kinase – Akt – mammalian target of rapamycin (PI3k-Akt-mTor, PAM) pathway as a possible common mechanism that may be the link in the inverse relation between AD and cancer in general." (PMID 31824268, 2019). "Furthermore, they further showed that LINC01554 down-regulation empowers cancer cells acquiring high aerobic glycolysis to sustain cells growth advantages via regulating PKM2 and Akt/mTOR signaling pathway." (PMID 31654067, 2019). "However, several works on cancer and neurodegenerative diseases have shown that PPARγ activation inhibits the PI3K/AKT/mTOR signaling pathway." (PMID 31993046, 2019). "Interestingly, PC1 regulates many signalling pathways including Jak/STAT, mTOR, Wnt, AP‐1 and calcineurin‐NFAT which are also used by cancer cells for sending signals that will allow them to acquire and maintain malignant phenotypes." (PMID 31251475, 2019). "In addition, the chromosomal locus containing miR-204 is frequently lost in cancers, resulting in its lower expression and resulted in BDNF/TrkB overexpression and activation of the AKT/mTOR/Rac1 signaling pathway." (PMID 31480771, 2019). "In contrast, phosphorylated mTOR (p-mTOR) and cIAP-1/2 proteins were up-regulated in drug-treated ALI multilayered co-cultures, suggesting an increase in some MDR features following exposure to anti-cancer drugs." (PMID 31464606, 2019). "Finally, we specifically examined which elements of the PI3K-Akt-mTOR signaling axis (involving PTEN, FMR1, NF1, TSC1, and TSC2) were dysregulated jointly in ASD and cancer." (PMID 31007884, 2019). "Our discovery that miR-3178 is suppressed by mTOR and targets CDC6 may provide one of the mechanisms of the deregulation of CDC6 in cancers." (PMID 31285446, 2019). "Oestrogen may act through the PI3K - protein kinase B (PKB, also known as AKT) - mammalian target of rapamycin (mTOR) pathway to induce NRF2 accumulation, supporting the emerging clinical strategy of treating BRCA1-related cancers with PI3K inhibitors." (PMID 30915162, 2019). "Considering how involved the mTOR signaling pathway is, it comes as no surprise that it also plays a crucial role in human disease, particularly cancer." (PMID 30764584, 2019).
cancer (continued). "These common pathways included general cancer-related pathways, such as pathways in cancer, proteoglycans in cancer, MAPK signaling pathway, Ras signaling pathway, Hippo signaling pathway, mTOR signaling pathway, Toll-like receptor signaling pathway, Wnt signaling pathway, and adherens junction." (PMID 31608109, 2019). "Recently, studies have documented that Akt-mTOR pathway could modulate HK2, a pivotal role in the procession of cancer metabolism, leading to tumor rapid growth, even in the presenceof oxygen." (PMID 31137633, 2019). "It has been shown that LAT1-mediated leucine uptake stimulates cancer cell proliferation activities through activating the mTOR signaling pathway, which has been considered as a reason why LAT1 functional inhibition reduce cell viability in various cancer cells." (PMID 31748583, 2019). "Preclinical research evidence supports that mTOR in conjunction with PI3K/Akt pathway regulates autophagy, a mechanism that could assist the body to remove malignant cells in cancer, and clear toxic proteins in AD." (PMID 30881282, 2019). "Hence, PI3K/AKT/mTOR pathway and HIF1-mediated hypoxic response are constitutively activated, contributing to glycolytic phenotype in cancer cells." (PMID 31366176, 2019). "CD44+/CD90+ cells have been identified as a unique population of cancer cells that may be required for the regulation of chemo- and radioresistance through PI3K and mTOR signaling." (PMID 31288154, 2019). "mTOR is the most typically activated downstream protein of the phosphoinositide 3-kinase (PI3K)/AKT pathway in response to the signaling of growth factors and is downregulated in a wide spectrum of human cancers." (PMID 31717694, 2019). "Our results were compatible with those of a previous study, which demonstrated that the activation of the PI3K/Akt/mTOR and MAPK/Erk pathways could promote cancer cell proliferation." (PMID 31118055, 2019). "Recent findings reveal that there is a complex interplay between the PI3K/AKT/mTOR signaling cascade, the regulation of HPV oncogene expression and the phenotypic response of HPV-positive cancer cells to E6/E7 repression, which all are dependent on the cellular metabolic and oxygenation status." (PMID 31058807, 2019). "In clinical trials of solid tumors, the PI3K/mTOR inhibitor NVP-BEZ235 (twice daily) is poorly tolerated, which leads to treatment discontinuation in some patients and limits its efficacy in treating cancer." (PMID 31277692, 2019). "VGF is an important regulator of metabolism and endoplasmic reticulum (ER) stress in neurons and endocrine cells, where it activates pro-survival signaling pathways such as PI3K/AKT/mTOR and MAPK/ERK1/2, but its role in regulation of cancer cells remained unclear for a long time." (PMID 31682594, 2019). "Given the pleiotropic effects of mTOR on cellular activity extensive research is being conducted on mTOR inhibitors as tools to treat not only neurodegenerative disorders, but also a wide range of metabolic disorders such as T2DM, cancer, and cardiovascular disease." (PMID 30684442, 2019). "Interestingly, AMPK, an important upstream signaling molecule of mTOR, is a metabolic switch that plays a key role in CD8+ T cell memory development during infection and cancer." (PMID 31825836, 2019). "Aberrant activation of the EGFR signaling pathway is critical for cancer cell apoptosis, proliferation, differentiation, and motility via the downstream RAS/RAF/MEK/ERK and AKT/PI3K/mTOR pathways, and tremendous amounts of research have implicated EGFR as a potential target for cancer therapy." (PMID 31608236, 2019). "In addition, SSD activates the Ca2+/calmodulin-dependent kinase/AMPK/mTOR pathway and attenuates STAT3/HIF-1 pathway signaling, which induces the apoptosis and inhibits the proliferation of cancer cells." (PMID 31781485, 2019).
cancer (continued). "In agreement with our results, autophagy was inhibited in TNFα-treated Caco-2 cells, and TNFα acted as an activator of mTOR via IκΒ-kinases involving or not AKT in different cancer cell models." (PMID 30546074, 2019). "The SLIT/ROBO pathway has important roles in tumorigenesis, cancer progression and metastasis and thus acts as a regulator for multiple oncogenic signalling pathways including the CD20, mTOR (mammalian target of rapamycin), VEGF and EGFR (epidermal growth factor receptors) pathways." (PMID 30857150, 2019). "Considering the emanent role of the PI3K/Akt/mTOR signaling cascade in controlling essential cellular functions, it is not an unanticipated finding, that in many cancers dysregulation can be found in this pathway." (PMID 31906235, 2019). "Preclinical tests have demonstrated that cancer cell lines derived from solid cancers became sensitive to hormone therapy, chemotherapy, or other targeted therapies when they are treated with PI3K or mTOR inhibitors." (PMID 31905960, 2019). "A murine NASH-HCC model was conducted and the obtained cancer cells (N-HCC25) were investigated towards chromosomal aberrations, the expression of cell type-specific markers, dependency on nutrients, and functional importance of mTOR." (PMID 31726709, 2019). "Recent data indicate that mTOR signaling modulates DNA damage response and hence DNA damage repair, providing an explanation for the fact that inhibiting RAS/PI3K-mTOR pathway sensitizes a lot of cancer cells to chemotherapy and radiotherapy." (PMID 31285446, 2019). "The PI3K/Akt/mTOR pathway is hyperactivated in many cancers, moreover, mTORC1 and ribosomal S6 kinase exert negative feedback to suppress hyperstimulation by growth factors." (PMID 31277491, 2019). "Taking into account the complexity of mTOR signaling networks, it is not hard to understand that the response to rapalogs varies in patients with cancer, such as metastatic RCC." (PMID 31277692, 2019). "Additionally, miR-221 modulates several gene targets involved in cancer-related pathways, including PTEN (P13K/AKT/mTOR), CDKN1B/p27, and CDKN1C/p57." (PMID 31681762, 2019). "EIF4A inhibitors (EIF4Ai), but not MTOR inhibitors, lead to specific translational reprogramming, which results in mitochondrial depolarization and cancer cell death." (PMID 30072418, 2019). "Also, the combinatorial anticancer potential of CTC along with pharmacological dual phosphatidylinositol 3-kinase (PI3K)-mTOR inhibitor, BEZ-235 was systematically examined in cancer cells." (PMID 30813295, 2019). "This was done by incubating all cancer cells with IgPKD1 for 3 hours, followed by collection and analysis of protein extracts at different time points (1, 3, and 6 hours) so as to investigate if the effect of PC1 on mTOR signalling is time‐dependent as well." (PMID 31251475, 2019). "The results of Western blot and flow cytometric assays indicate that the flavonoid fisetin (3, 3′, 4′, 7-tetrahydroxyflavone) effectively suppresses the apoptosis, metastasis, angiogenesis and invasion of cancer cells via ERK1/2-, Akt/NF-κB/mTOR- and p38 MAPK-dependent NF-κB signaling pathways." (PMID 31781485, 2019). "Furthermore, downstream signal-dependent transcription factors activated by PI3K/AKT/mTOR signaling, such as MYC and NRF1, stimulate transcription of cell proliferation and metabolic genes allowing cancer cell growth." (PMID 31315653, 2019). "Furthermore, KLB down genes were identified, which involved those in cell cycle, DNA replication and packaging, cell division, WNT signaling and other cancer-related pathways such as MYC, VEGF-A and MTOR." (PMID 31695781, 2019).
cancer (continued). "mTOR inhibitors failed as an anti-cancer drug due to suppression of the negative feedback loops from mTOR and S6, hence reversing the anti-proliferative effects of the inhibitor." (PMID 31277491, 2019). "Current literature provides further evidence that glutamine in cancer facilitates exchange of EAAs (essential amino acids) with glutamine into proliferating cells via glutamine transporters, which induces mTOR (mammalian target of rapamycin) activation in NSCLC and other types of cancer." (PMID 30871192, 2019). "Recently, the mTOR inhibitors temsirolimus and everolimus and the PI3K inhibitors idelalisib and copanlisib have been approved by the FDA for clinical use in the treatment of a number of different cancers." (PMID 31254443, 2019). "Additional treatment with the mTOR pathway inhibitor rapamycin significantly potentiated the toxic effects of the SA/GT11 combination, indicating a cooperative effect of the two pathways in inducing cancer cell death." (PMID 31332161, 2019). "Everolimus, an inhibitor of mTOR, has emerged as a potential combination therapy drug for the treatment of cancer that does not respond to conventional therapy." (PMID 31480338, 2019). "Results of studies from many centres on a panel of human cancer cell lines of different histological origin confirmed the role of PTEN status in determining pharmacological interactions between RAF/MEK and PI3K/AKT/mTOR pathways inhibitors." (PMID 30848427, 2019). "Targeting the mTOR and MNK-eIF4E pathways may provide important new opportunities for new cancer therapeutic approaches." (PMID 31903169, 2019). "Since TIPRL is reported to be closely related to the mTOR pathway, we employed Earle’s balanced salt solution (EBSS) as a starvation model to induce metabolic stress and elucidate the regulation mechanism of TIPRL on cancer cell growth." (PMID 31862913, 2019). "Together, these data suggest that the effects of mTOR inhibitors on CSC may be dependent on the genetic background and rewiring of cancer stemness pathways." (PMID 31277692, 2019). "piR-55490 binding to the 3′-UTR of mTOR inhibits the expression of mTOR and its target genes, HIF-1, PGC-1α, and PPARγ, reducing LC cell and tumor proliferation, as the Akt/mTOR signaling pathway is a key cancer biology pathway." (PMID 31399034, 2019). "PC1 knockdown resulted in significantly affecting the phosphorylation of only one mTOR pathway component in most cancer cell lines; therefore, based on our data, PC1 appears to down‐regulate mTOR signalling in PC3 and HT29 cells, while it up‐regulates mTOR signalling in GOS3 and A549 cells." (PMID 31251475, 2019). "Cancer stem cells, CD44+/CD90+ cells, yield elevated mEAK-7 and activated mTOR signaling." (PMID 31288154, 2019). "Regardless of the location within the tumor, cancer tissue showed higher expression of mTOR, p-mTOR, and 4EB-P1 compared to benign tissue (p < 0.01)." (PMID 31885728, 2019). "Moreover, inhibitors of PI3kγ, a molecule upstream of mTOR, are able to promote TAM-immunostimulatory responses in several cancer models." (PMID 31547627, 2019). "The suppression of the Akt/PI3K/mTOR axis, even in the presence of EGF, could be a promising finding in the field of cancer therapy research." (PMID 30766532, 2019). "1,25(OH)2D3 has been stated to upregulates HIF-1α via mTOR signaling in human monocytes and breast epithelial cells, while other studies uncovered that HIF-1α status is attenuated by 1,25(OH)2D3 treatment in human cancer cells." (PMID 30813930, 2019).